TNF (tumor necrosis factor)
Diseases named in the same sentence as TNF in open-access papers (continued):
Sharing a sentence is not in itself a finding about the gene and the disease.
liver fibrosis (continued). "Activated HSCs are identified by the overexpression of α-SMA and extreme expression of extra cellular matrix proteins (vimentin, β-catenin, and snail) through inflammatory cytokines such as TNF-α, IL-1β, and IL6, which increase the development of liver fibrosis." (PMID 37090196, 2023). "In summary, CVC may ameliorate inflammatory macrophage and neutrophil accumulation and liver fibrosis via the JAK-STAT1, TNF-NFκB, and MAPK signaling pathways." (PMID 37215993, 2023). "Similarly, it has been recorded that vinpocetine efficiently reduced increased levels of hepatic IL-6, TNF-α, and TGF-β1, in a rat model of hepatic fibrosis." (PMID 36594060, 2023). "It was found that liver TNF-α mRNA expression in NASH patients with liver fibrosis was stronger than that in NASH patients without fibrosis." (PMID 35422858, 2022). "In this study, we found that TRPM8 inhibition could reduce the F4/80 positive cell population and inhibit the transcript levels of IL-6, IL-1β, TNFα, and MCP-1 in murine models of liver fibrosis." (PMID 35525986, 2022). "Besides TNFα, transforming growth factor (TGF)-β is a major regulator of liver fibrosis and cirrhosis." (PMID 35215790, 2022). "Our previous study demonstrated the mitigative effect of PZH on experimental liver fibrosis on bounding up with the regulation of HSC activation and many inflammatory signaling [such as tumor necrosis factor (TNF)-α, nuclear factor kappa-light-chain-enhancer of activated B (NF-κB)]." (PMID 36188553, 2022). "This study discovered that the proportion of DNTs in peripheral blood of liver fibrosis patients significantly increased and that DNTs secreted TNF-α to promote the activation of the TNFR1-NLRP3 axis and regulate HSC activation, thus leading to liver fibrosis progression." (PMID 35371052, 2022). "Consistently, the mRNA levels of inflammatory mediators TNF-α and IL-1β, as well as IL-6, ICAM, CCL2, CXCL2, and TGF-β, which were indicated as progressive inflammatory response and liver fibrosis, were significantly elevated in the liver of MFG-E8 knockout mice compared with the MCD-WT group." (PMID 35769208, 2022). "The global cytokine surveys of HSC-CM have demonstrated that TNF-α, agrin, PDGF, activin A, GM-CSF, IFN-γ, IL-1β, IL-4, IL-6, IL-10, IL-13, and TIMP-1, which subsequently induce acute inflammation and liver fibrosis, were elevated in aHSC-CM relative to the qHSC-CM." (PMID 36142683, 2022). "PA could also significantly up-regulate SOD and GSH-px levels (p<0.01), down-regulate IL-1β, IL-18, caspase-1, NLRP3, and TNF-α protein or gene expression in PBC mice (p<0.01) and inhibit liver fibrosis levels (p<0.01)." (PMID 35195182, 2022). "Emodin can lessen the severity of liver fibrosis by decreasing the infiltration of Gr1hi monocytes and drastically reducing the production of granulin (GRN), monocyte chemoattractant protein 1 (MCP-1), TNF-α, TGF-β1, and chemokine ligand 7 (CCL7) in the liver." (PMID 36435779, 2022). "Furthermore, it has been reported that overexpression of TTP attenuates liver fibrosis by degrading MMP-2 and TNFα." (PMID 36148947, 2022). "The conversion of Ly6Chi to Ly6Clo macrophages significantly downregulated the expression levels of Ly6Chi macrophage-derived PDGF, TNF-α, and IL-1β in the fibrotic liver, which was accompanied with the reduced expression of HSC-derived α-SMA and Col1α1 and the reduction of liver fibrosis." (PMID 34518510, 2021). "In vivo, liver injured tissue promotes inflammatory processes that stimulate MSCs to release various growth factors and cytokines such as HGF, EGF, IL-6 and TNF-α, and among them, HGF plays a well-established role in liver pathogenesis by attenuating liver fibrosis in various in vivo models." (PMID 33466583, 2021). "The first study to show a link between TNF (early studies do not clarify the member of the TNF family measured) and hepatic fibrosis was in Brazil." (PMID 33790908, 2021).
liver fibrosis (continued). "The therapeutic effects of IL-10 were shown in experiments in vivo in which IL-10 gene therapy reduced the expression of fibrosis-related genes including TGF-β, TNF-α, and collagen α1, and also decreased the activation of α-SMA in thioacetamide-induced liver fibrosis." (PMID 33841164, 2021). "The elevation in TNF-α, IL-6, NF-κB and TGF-β lead to liver fibrosis." (PMID 34969385, 2021). "Our data showed that PHI had a good anti-inflammatory effect in mice with CCl4-induced liver fibrosis, which represented as the reduction of serum LPS, MIP-1 and TNF-α levels as well as the decreased expressions of three inflammatory factors (IL-1β, IL-6, and TNF-α) in liver tissue." (PMID 34621179, 2021). "Despite that, IL-12 and TNF showed a positive correlation with liver damage parameters (such as elastography and liver fibrosis scores), and negative correlations with clinical variables that assess early metabolic disorders." (PMID 34447378, 2021). "Also many papers showed with regard to this that different priming approaches, such as 3D cultures of MSCs, IFN-γ and TNF-α treatment, enhance the MSCs production of HGF, making them a potential therapeutic tool to treat liver fibrosis." (PMID 33466583, 2021). "By adopting the TGF-β1 inhibitor pirfenidone, TNF-α inhibitor pentoxifylline, and monocytes depressor clodronate-loaded liposomes in p65Δhepa/PUMA-WT mice, we found inhibition of inflammatory action ameliorated liver fibrosis." (PMID 33980818, 2021). "Furthermore, we detected the levels of TLR4, NF-κB, TNF-α, TGF-β, IL-10, α-SMA, and collagen I to study the degree of liver fibrosis in rats." (PMID 32226380, 2020). "In vivo study revealed that liver fibrosis was inhibited by HQD plus BMSCNumb-KD treatment, while Hyp content in liver tissue, the gene and protein expression of α-SMA, gene expression of Col I, TNF-α, and TGF-β1 were increased compared to that in HQD group." (PMID 33060633, 2020). "Peng's research demonstrated that 70 mg/kg baicalin had a significant effect on CCl4-induced liver fibrosis, which was correlated with immunoregulation of the imbalance between profibrotic and anti-fibrotic cytokines, including TGF-β1, TNF-α, IL-6, and IL-10 expression." (PMID 33082829, 2020). "Moreover, silymarin relieved diet-induced NASH with liver fibrosis by suppressing HSC activation and TNF-α release." (PMID 33082829, 2020). "In the liver, tenascin-C knockout mice with liver fibrosis induced by concanavalin A showed protection against collagen deposition and inflammatory cell infiltration, reduced IFN-γ, TNF, IL-4, and TGF-β1 production, and a lower number of activated HSCs in respect to wild type animals." (PMID 33262757, 2020). "Kupffer-derived TNFα was found to enhance HSC cell survival, which in turn promotes liver fibrosis." (PMID 32160239, 2020). "Our results showed that EP could inhibit HSC activation as EP significantly downregulated the HMGB1 level at 4 and 6 weeks of liver fibrosis induced by BDL, while IL-1β and TNF-α levels decreased substantially." (PMID 31933629, 2019). "Therefore, serum TNF-α and IL-6 play an important role in the development of TAA-induced hepatic fibrosis." (PMID 31362375, 2019). "Matrine prevented MCD diet-induced inflammation and fibrosis in the liver after 6 weeks of treatment, as demonstrated by a matrine-induced suppression of the increases in TNFα, CD68, MCP-1 and NLRP3, and hepatic fibrosis proteins (TGFβ, Smad3, and collagen 1) induced by MCD diet." (PMID 31068812, 2019). "They further showed that antagonizing both IL-1 and TNF-α was essential to significantly reduce NF-κB in HSCs and reduce liver fibrosis in a BDL model (no data in the CCl-4 model)." (PMID 30875826, 2019). "KC have an essential role in liver fibrosis in mouse models of ASH and NASH, propagating hepatic inflammation via tumor necrosis factor (TNF) and leukocyte recruitment via intercellular adhesion molecule-1 (ICAM-1) and vascular cell adhesion molecule-1 (VCAM-1)." (PMID 30972062, 2019).
liver fibrosis (continued). "In addition, the proinflammatory factor TNF-α promoted the expression of TGF-β1, and further resulted in liver fibrosis." (PMID 30781895, 2019). "It was noteworthy that OA’s derivatives, such as CPU-II2, CDDO-EA, and Oxy-Di-OA, could attenuate the expression of TNF-α, α-SMA and TGF-β, and improve histologic and serologic markers of fibrosis in CCl4-induced hepatic fibrosis in rats." (PMID 29393898, 2018). "Macrophages located almost exclusively in areas of liver tissue scarring are a major source of MMP13 and can resolve liver fibrosis both directly by production of MMP13 and indirectly by secretion of cytokines, such as TNF-α and IL-1, which regulate MMP13 production by other cells." (PMID 30034399, 2018). "The induction of hepatocyte apoptosis is crucial for liver fibrosis, as inhibition of hepatocyte apoptosis by treatment with antimicrobials, TNF-α knockdown, or overexpression of constitutively active inhibitor of nuclear factor kappa-B kinase (IKK) 2 results in reduced liver fibrosis." (PMID 30308992, 2018). "However, emodin administration was able to decrease the hepatic expression of IL-1β, TNF-α, GRN, and TGF-β1 in the liver fibrosis model, which also explains why emodin can alleviate liver inflammation and fibrosis." (PMID 29743924, 2018). "It is also possible that the effect of p21 knockout on liver fibrosis derives from its ability to influence the viability of senescent cells and to regulate the microenvironment by directly controlling the production of ECM components and by secreting TNF‐α." (PMID 28607003, 2017). "In vivo studies showed that inhibition of TNF-α has antifibrotic effect in animals, however, the role of TNF-α in liver fibrosis, whether profibrotic or antifibrotic, is still controversial." (PMID 28953991, 2017). "Nonetheless, several other studies found that TNF-α-mediated apoptosis was not involved in the progression of liver fibrosis." (PMID 27420058, 2016). "The toxic metabolite of CCl4 can activate Kupffer cells to secrete cytokines such as interleukin-1 (IL-1) and tumor necrosis factor-α (TNF-α), stimulate transforming growth factor-β (TGF-β) production, inhibit nitric oxide (NO) formation and induce inflammation and liver fibrosis." (PMID 25344394, 2014). "However, the roles of TNF-α on hepatic stellate cell (HSC) activation and liver fibrosis are complicated and remain controversial." (PMID 23755201, 2013). "In contrast to those reports, our study found a reduction of liver fibrosis after CBDL+CDL in TNF-α−/− mice without a reduction in liver injury." (PMID 23755201, 2013). "The profibrogenic effects of TNF-α in another fibrosis model, which uses CCl4, have been reported previously, indicating that TNFR1 deficiency inhibits liver fibrosis after CCl4 treatment, without any effects on liver injury." (PMID 23755201, 2013). "It is well established that the Th1 cytokines, IFN-gamma and TNF-alpha, both trigger the release of soluble ICAM-1 (sICAM-1) and are known to play key roles in the modulation and aggravation of hepatic fibrosis, respectively." (PMID 18001742, 2008). "Among these inflammatory cytokines, IL-6, TNF, and TGF-β play crucial roles in maintaining immune responses, tissue repair, and homeostasis, serving as key pro-inflammatory and pro-fibrotic factors that activate hematopoietic stem cells and drive liver fibrosis." (PMID 40778202, 2025).
liver fibrosis (continued). "Furthermore, pre- infection with T. spiralis markedly reduced S. mansoni- induced hepatic fibrosis, as evidenced by decreased collagen deposition, low expression of α-SMA, and significantly reduced levels of IL-17, IL-1B, IL-6, TGF-B, IL-23, and TNF-α compared to mice infected with S. mansoni only." (PMID 39439825, 2024). "The perivascular inflammatory cell infiltration and liver fibrosis area in TNF-Tg mice were significantly higher than those in WT mice, which could not be reduced by anti-TNF treatment." (PMID 37784156, 2023). "TRIM38 directly binds to TAB2, and recognizes the K63 of RIP1 in the TNF-α signaling pathway through TAB2 to connect the ubiquitin chain or TRAF6 in the IL-1β signaling pathway, thereby inhibiting the key pathway TAK1-MAPK cascade in the process of liver fibrosis." (PMID 37867509, 2023). "Moreover, our data revealed that TNF-α/IL-1β upregulated COX-2 expression and PGE2 production, while COX-2 silence reversed the reinforced ability of TNF-α/IL-1β-pretreated hADSCs to attenuate liver fibrosis." (PMID 37095581, 2023). "The reduction in hepatic fibrosis may be connected with reductions in transforming growth factor beta (TGF-β) and tumor necrosis factor-alpha (TNF-α) levels, especially the former, which plays an important role in the progression from NAFLD to non-alcoholic steatohepatitis." (PMID 36902639, 2023). "In our study, PG545 significantly reduced the level of TNF-α, and both heparanase inhibitors decreased Casp3 and LC3 levels, effects that are expected to suppress the inflammatory and the pro-fibrotic responses and result in decreased ECM deposition, leading to prevention of liver fibrosis." (PMID 35329997, 2022). "On this note, elevated oxidative stress has been shown to promote liver fibrosis by stimulating the generation of collagen from the activated hepatic stellate cells and release of other profibrotic (TGF-β, α-SMA), chemotaxis (MCP-1) and proinflammatory (IL-1β, TNF-α) mediators." (PMID 34427662, 2021). "Moreover, the core targets were predominantly related to several KEGG pathways, such as apoptosis-related, liver disease (NAFLD, hepatitis B and hepatocellular carcinoma)-related, TNF, VEGF, NF-κB, and MAPK pathways, implicating their involvement in the effects of SNS on liver fibrosis." (PMID 34276360, 2021). "It is also reported that TNF-α is involved in hepatic fatty acid synthesis, increases serum triglyceride level, activates the production of VLDL from the liver and stimulates both hepatocytes’ cell death and proliferation, thus, is crucially involved in the pathogenesis of liver fibrosis." (PMID 34943134, 2021). "Decreasing the levels of IL-1β, IL-6, and TNF-α could alleviate CHI and hepatic fibrosis." (PMID 33144872, 2020). "In this study, we showed that lnc-Lfar1 silencing alleviated liver injury-induced upregulation of LY6C, IL-1β, IL-6, TNF-α, MCP-1, CCL5 and CXCL10 in vivo and in vitro, suggesting that lnc-Lfar1 knockdown might be beneficial for preventing liver fibrosis by targeting these chemokines." (PMID 32071306, 2020). "Furthermore, TNF-α is considered to be a crucial factor for the development and progression of NAFLD and steatohepatitis through the upregulation of molecules related to inflammatory cytokines, lipid metabolism, and liver fibrosis." (PMID 30022981, 2018). "In addition, BAR502 reduced liver fibrosis scores by 70% and expression of pro-fibrogenetic genes (αSMA and α1-collagen), as well as the inflammatory score and liver expression of F4/80, IL-1β, IL-6, MCP-1, RANTES and TNFα mRNA." (PMID 28202906, 2017). "Neutralization of IL-9 in mice ameliorated hepatic fibrosis, attenuated the activation of hepatic stellate cells, reduced frequencies of Th9, Th17 and Th1 cells in spleen, and suppressed expression of IL-9, IL-17A, IFN-γ, TGF-β1, IL-6, IL-4 and TNF-α in plasma and liver respectively." (PMID 26728971, 2016).
liver fibrosis (continued). "TNF-α is involved in disparate processes, including apoptosis, cell survival, inflammation and immunity and may be an important initial step towards RILD and liver fibrosis." (PMID 25483171, 2015). "Thus, targeting TNF-α and TIMP-1 may become a new therapeutic strategy for treating liver fibrosis in cholestatic liver injury." (PMID 23755201, 2013). "Thus, targeting TNF-α and TIMP-1 may become a new therapeutic strategy for treating liver fibrosis and cholestatic liver injury." (PMID 23755201, 2013). "The intricate relationships among TNF‐α, IL‐6, CCL2, and TGF‐β through positive feedback loops and synergistic interactions create a persistent fibrotic environment, suggesting that a multifaceted therapeutic approach may be necessary to address liver fibrosis effectively." (PMID 41487942, 2026). "The present study showed that CLEE could protect rats against TAA-induced liver fibrosis and kidney injury probably by (i) reduction of MDA, (ii) enhancement of GSH and CoQ10; and (iii) inhibition of the increase of inflammatory markers, IL2, CPR, TNF-α, NO that evoke oxidative stress." (PMID 36235007, 2022). "Likewise, in a recent study, mRNA and protein levels of IQGAP1 were shown to be significantly elevated in CCl4-induced liver fibrosis mice and TNF-α-treated hepatic stellate cell (HSC) line, LX-2 cells, which might be related to the development and advancement of liver fibrosis." (PMID 35785216, 2022). "Thus current results suggested that MMP2, MMP9 and TNF-α could be considered as potential markers of inflammation but not of the degree of liver fibrosis in chronic HCV patients." (PMID 26464613, 2015). "FZHY suppressed hepatocyte apoptosis elicited by CCl4in vivo or ActD/TNF-α in vitro through regulating mediators in death receptor and mitochondrial pathways, and this action on hepatocyte apoptosis might play an important role on HSC activation and liver fibrosis." (PMID 25407538, 2014). "They emphasized that IL-1 and TNF did not promote HSC activation but promoted the survival of activated HSCs in vitro as well as in vivo and thereby increased liver fibrosis." (PMID 36769672, 2023). "BDL did not induce significant liver injury or liver fibrosis in TNF-α−/− mice and TNF receptor 1 (TNFR1)−/− mice, suggesting that TNF-α is significantly involved in the pathophysiology following BDL." (PMID 31847135, 2019). "There was a significant decrease in the protein levels of TNFα, IL‐6 and IL‐17 (P < 0.01) in CCI4 treated fibrosis‐induced mice injected with Exo‐181 compared to the liver fibrosis mouse model without exosome treatment." (PMID 28382720, 2017). "IL-1 and TNF-α did not promote HSC activation but promoted survival of activated HSCs in vitro and in vivo and thus increased liver fibrosis." (PMID 24978432, 2014). "Interestingly, supplementation with DHBA failed to increase the level of ALT/AST, TNF-α/IL-6, or TGF-β1/α-SMA/COL1A1 in CCl4-challenged GPR81 KO mice, suggesting that the detrimental effects of DHBA on CCl4-induced liver fibrosis depend on GPR81." (PMID 38982366, 2024). "In the present study, we also found that the TNFα but not the TGFβ induced expressions and secretions of WISP1v1 and WISP1v2, respectively, in HPrF cells, although reports have indicated that WISP1 is a downstream gene of TGFβ in the studies of primary lung fibroblasts and liver fibrosis." (PMID 36232736, 2022). "TNF-α is one of the main pro-inflammatory cytokines involved in systemic inflammation and it has been significantly related to non-alcoholic steatohepatitis (NASH) and hepatic fibrosis, playing a key role in the progression of non-alcoholic fatty liver disease." (PMID 36616158, 2022). "The effect of PGRN on liver fibrosis has not been investigated, but based on these findings, it is conceivable that PGRN might inhibit inflammation during chronic liver disease by modulating tumor necrosis factor-α (TNF-α) signaling." (PMID 31591383, 2019).
liver fibrosis (continued). "However, it is still unclear whether the reduced liver fibrosis is due to a lack of fibrogenic effects of TNF-α or due to the reduced liver injury because previous reports indicate that both liver injury and fibrosis after CBDL are reduced in TNF-α−/− mice and TNFR1−/− mice." (PMID 23755201, 2013).